THEMIS2 (thymocyte selection associated family member 2)
Diseases named in the same sentence as THEMIS2 in open-access papers:
THEMIS2 is named in the same sentence as 20 diseases in open-access papers, as found by Europe PMC text mining. Sharing a sentence is not in itself a finding about the gene and the disease. The quoted sentences say what the papers report.
ovarian carcinoma (4 papers, 2010 to 2024). A malignant neoplasm originating from the surface ovarian epithelium. "The suppression of THEMIS2 expression not only disrupts EMT-associated molecular markers but also hampers the migratory and invasive capabilities of ovarian cancer cells." (PMID 38175687, 2024). "To investigate this further, we performed in vitro experiments wherein THEMIS2 was silenced in ovarian cancer cells." (PMID 38175687, 2024). "In this study, we successfully enriched CSC lines from three established human TNBC and two ovarian cancer lines and identified THEMIS2 to be the sole common gene with increased expression in the five CSCs enriched lines." (PMID 34974522, 2022). "The transcription of THEMIS2 is estrogen-responsive and the knockdown of THEMIS2 enhances estrogen responsiveness in both breast and ovarian cancer cells." (PMID 34974522, 2022). "Themis2 mRNA expression is also reported to be regulated by IFNγ or estrogen treatment of ovarian cancer cell lines." (PMID 20644716, 2010). "Moreover, the inhibition of THEMIS2 significantly impeded the migration and invasion of ovarian cancer cells." (PMID 38175687, 2024). "To assess whether Themis2 was necessary for LPS-induced TNF production in primary human macrophages we used two siRNAs previously shown to inhibit Themis2 mRNA expression in a human ovarian cancer cell line." (PMID 20644716, 2010).
breast carcinoma (2 papers, 2022 to 2023). "Increased THEMIS2 expression was associated with poor survival in TNBC patients and in patients from our breast cancer cohort." (PMID 34974522, 2022). "The IHC score of THEMIS2 was significantly higher in the breast cancer tissues than in the normal tissues." (PMID 34974522, 2022). "Because no studies have reported correlations between THEMIS2 and MET activity in breast cancer thus far, we assessed their clinical connection by examining THEMIS2 and p-MET protein levels in breast cancer tissue specimens." (PMID 34974522, 2022). "The THEMIS2 protein levels in 465 pairs of breast cancer tissue specimens and the adjacent normal tissues from our local cohort were determined through IHC staining." (PMID 34974522, 2022). "Kaplan–Meier survival analysis of the 465 cases revealed that breast cancer samples with higher THEMIS2 levels were correlated with significantly poorer survival than were those with lower THEMIS2 levels." (PMID 34974522, 2022). "Moreover, the correlation between THEMIS2 mRNA expression and the overall survival of breast cancer patients was assessed through a web server program, as described in the Methods section." (PMID 34974522, 2022). "Since MCF-7 cells possess both estrogen and progesterone receptors and our data are mainly applied to TNBC cells, lack of hormone receptors might affect the regulatory function of THEMIS2 in breast cancer cells and warrants further investigation." (PMID 34974522, 2022). "THEMIS2 has been reported to be involved in estrogen responses in ovarian and breast cancer cells." (PMID 34974522, 2022). "Finally, we explored the correlations between THEMIS2 expression levels and clinical outcomes of breast cancer patients." (PMID 34974522, 2022). "In addition, THEMIS2 could be a potential biomarker and target for breast cancer treatment guidance with respect to ER status." (PMID 34974522, 2022). "Expression levels of THEMIS2 and p-MET protein were positively correlated in the 465 breast cancer specimens." (PMID 34974522, 2022). "Levels of THEMIS2 and p-MET protein were significantly correlated in the 465 breast cancer specimens." (PMID 34974522, 2022). "Furthermore, expression of THEMIS2 correlated with poor clinical outcomes in TNBC patients and breast cancer patients." (PMID 34974522, 2022). "To test that THEMIS2 might regulate hormone receptor positive breast cancer cells, such as MCF7, we performed an additional MTT assay and observed knockdown or overexpress THEMIS2, increase or decrease slightly, respectively, the growth of MCF-7 cells." (PMID 34974522, 2022).
Arthritis (1 paper, 2010). Inflammation of a joint. "We measured Themis2 protein expression in adherent (macrophage-enriched) or non-adherent (B cell-enriched) splenocyte populations in a murine model of arthritis." (PMID 20644716, 2010). "Using a collagen-induced arthritis model, mice immunised with collagen but failing to develop arthritis exhibited no change in Themis2 expression." (PMID 20644716, 2010).
glioblastoma (1 paper, 2025). The most malignant astrocytic tumor (WHO grade IV). "Specifically, in the CGGA dataset, we observed that a high THEMIS2 expression was associated with poorer survival in patients with MGMT-methylated glioblastoma." (PMID 39851494, 2025). "Our findings suggest that a high THEMIS2 expression correlates with poorer survival in MGMT-methylated glioblastoma patients, potentially offsetting the survival advantage typically associated with MGMT methylation." (PMID 39851494, 2025). "This may contribute to the formation of an immunosuppressive microenvironment in glioblastoma, providing crucial insights into the potential role of THEMIS2 in immune regulation." (PMID 39851494, 2025).
hepatocellular carcinoma (1 paper, 2023). A malignant tumor that arises from hepatocytes. "In addition, studies have found that lncRNA THEMIS2-211 is highly expressed in hepatocellular carcinoma (HCC) and has a connection with the poor prognosis of HCC patients." (PMID 36755803, 2023).
liver inflammation (1 paper, 2023). "Our study shows that the expression of THEMIS2 has a significant and positive connection with the degree of plasma cell-, neutrophil-, and NK cell-activated infiltration, which may explain how THEMIS2 is involved in the immune pathway of liver inflammation." (PMID 36755803, 2023).
osteoarthritis (1 paper, 2022). A noninflammatory degenerative joint disease occurring chiefly in older persons, characterized by degeneration of the articular cartilage, hypertrophy of bone at the margins and changes in the synovial membrane. "Among them, SPAG5, CUX2, and THEMIS2 were identified as tissue-specific expressed hub genes, these 3 tissue-specific expressed hub genes have superior diagnostic value in the RA samples compared with osteoarthritis (OA) samples." (PMID 35368701, 2022).
parasitic infection (1 paper, 2020). "Genetic variants of interest identified in several immune related genes for all the antibody response and parasitic infection traits: IBDV (TOLLIP, ANGPTL5, BCL9, THEMIS2), MDV (GRM7), SG (MAP3K21), Eimeria (TOM1L1), and cestodes (TNFAIP1, ATG9A, NOS2)." (PMID 33193617, 2020).
rheumatoid arthritis (1 paper, 2010). A chronic, systemic autoimmune disorder characterized by inflammation in the synovial membranes and articular surfaces. "As such, Themis2 could represent a novel site at which therapies designed to intervene in chronic inflammatory diseases involving TNF, such as rheumatoid arthritis, might usefully be targeted." (PMID 20644716, 2010).
thyroid cancer (1 paper, 2024). "Patients with diminished THEMIS2 expression exhibited poorer survival outcomes, suggesting that THEMIS2 expression may serve as a diagnostic and prognostic marker for thyroid cancer." (PMID 38589421, 2024). "Finally, we defined THEMIS2 as a diagnostic biomarker of thyroid cancer because AUC exceeded 0.65 (AUC = 0.677)." (PMID 38589421, 2024). "The results revealed a significant positive correlation between THEMIS2 expression in thyroid cancer and the expression of these immune checkpoints." (PMID 38589421, 2024). "The mRNA expression of THEMIS2 was lower in patients with thyroid cancer aged ≥ 55 years than in those aged < 55 years." (PMID 38589421, 2024). "Based on the three prognosis-related variables, including age, clinical stage, and THEMIS2 expression, a nomogram model was established for the prognostic assessment of thyroid cancer." (PMID 38589421, 2024). "THEMIS2 is overexpressed in thyroid cancer tumor samples and demonstrates remarkable discriminatory ability between cancerous and healthy controls, as indicated by the findings of our bioinformatics research." (PMID 38589421, 2024). "THEMIS2 exhibits strong correlations with age and tumor type and is significantly upregulated in thyroid cancer tumors." (PMID 38589421, 2024). "Univariate Cox regression analysis demonstrated age, stage, and THEMIS2 expression as important factors of prognosis of patients with thyroid cancer." (PMID 38589421, 2024). "Interaction analysis suggested that the prognostic effect of THEMIS2 in thyroid carcinoma is primarily affected by age and stage." (PMID 38589421, 2024). "This could be attributed to the fact that THEMIS2 is derived from module genes correlated strongly with age and different types of thyroid cancer." (PMID 38589421, 2024). "We investigated the prognostic value of THEMIS2 expression in thyroid cancer." (PMID 38589421, 2024). "Univariate and multiple Cox regression analyses were performed to determine whether THEMIS2 expression was an independent predictor of thyroid cancer." (PMID 38589421, 2024). "We investigated THEMIS2’s prognostic significance in thyroid carcinoma." (PMID 38589421, 2024). "Thus, THEMIS2 was a biomarker of immune infiltration and prognosis in thyroid cancer." (PMID 38589421, 2024).
triple-negative breast carcinoma (1 paper, 2022). An invasive breast carcinoma which is negative for expression of estrogen receptor (ER), progesterone receptor (PR), and human epidermal growth factor receptor 2 (HER2). "THEMIS2 was identified as the sole common elevated gene in three triple negative breast cancer (TNBC) and two ovarian CSC lines." (PMID 34974522, 2022).
cancer (6 papers, 2014 to 2025). A tumor composed of atypical neoplastic, often pleomorphic cells that invade other tissues. "We also discovered a novel mechanism with regard to the regulatory function of THEMIS2 in enhancing MET activation phosphorylation to regulate cancer stemness by suppressing the association of PTP1B with p-MET." (PMID 34974522, 2022). "In short, in TNBC, CPT potently inhibited cancer stemness properties and cell invasion through the downregulation of the THEMIS2/MET signaling pathway." (PMID 34974522, 2022). "Consistent with the promotion of cancer cell migration/invasion by THEMIS2, overexpression of THEMIS2 in MDA-MB-231 cells greatly increased their lung metastatic ability." (PMID 34974522, 2022). "In short, we discovered that THEMIS2 controls cancer stemness and chemoresistance mainly by regulating PTP1B–p-MET interaction and MET activation." (PMID 34974522, 2022). "In summary, we have identified THEMIS2 as a novel regulator of cancer stemness and chemoresistance through interfering with the association of PTP1B with p-MET to promote MET signaling in TNBC cells." (PMID 34974522, 2022). "This is the first report revealing the inhibitory effect of cryptotanshinone (CPT), a powerful STAT3/STAT5 inhibitor, on THEMIS2–MET axis leading to inhibition of cancer stemness and lung metastasis." (PMID 34974522, 2022). "We found that non-cytotoxic dosages of cryptotanshinone (CPT) could potently inhibit cancer stemness, chemoresistance and tumorigenicity by suppressing expression of THEMIS2." (PMID 34974522, 2022). "We further employed MTT assay and sphere formation assay to evaluate whether THEMIS2 could affect cancer cell proliferation and sphere forming abilities." (PMID 34974522, 2022). "Next, we tested the effect of CPT on THEMIS2 promoted TNBC cancer metastasis." (PMID 34974522, 2022). "For the first time, we demonstrated that THEMIS2 specifically enhanced MET activating phosphorylation by suppressing the association of protein-tyrosine phosphatases 1B (PTP1B) with p-MET and MET, which accounted mainly for THEMIS2-mediated effect on cancer stemness and chemoresistance." (PMID 34974522, 2022). "Because Capmatinib therapy showed efficacy in patients with NSCLC and MET is well established in the etiology of this cancer type, it would be of interest to further determine whether the THEMIS2-MET axis also exists in this tumor type." (PMID 34974522, 2022). "The researchers identified THEMIS2 as a novel regulator of cancer stemness and chemoresistance by disrupting the interaction between PTP1B and p-MET, thus promoting MET signaling in cancer cells." (PMID 38175687, 2024). "However, THEMIS2 is upregulated in the CSCs of the TNBC and OC cell lines, and it augments cancer stemness and chemoresistance by releasing PTP1B from MET in TNBC." (PMID 40182754, 2025). "In this study we have identified THEMIS2 as a novel modulator of cancer stemness and chemoresistance, revealed its regulatory mechanism in MET activation, and suggested a relevant clinical application using CPT or Capmatinib to target THEMIS2/MET axis." (PMID 34974522, 2022). "Although THEMIS2 plays a role in inflammation, its specific actions and mechanism in regulating cancer stemness, metastasis, and recurrence has never been studied." (PMID 34974522, 2022). "Considering that CPT inhibited cancer stemness by suppressing THEMIS2 expression and MET phosphorylation activation, we investigated whether the inhibition of endogenous THEMIS2 expression could affect the chemosensitivity of TNBC cells with effects mimicking those of the CPT treatment." (PMID 34974522, 2022).
tumor (6 papers, 2022 to 2025). "In this study, we are the first to identify THEMIS2 as a key regulator of tumor-associated macrophage (TAM)-mediated immunosuppression in GBM." (PMID 39851494, 2025). "All these features of Themis2-deficient NK cells appear beneficial for anti-viral and anti-tumor immunity." (PMID 37938555, 2023). "A high THEMIS2 expression was associated with elevated scores, suggesting that higher THEMIS2 expression may reflect a more immune-enriched and stroma-enriched tumor microenvironment." (PMID 39851494, 2025). "Additionally, single-cell RNA sequencing data demonstrated that macrophages with a high THEMIS2 expression were associated with increased phagocytosis, immune suppression, and enhanced tumor growth." (PMID 39851494, 2025). "Receiver operating characteristic curve (ROC) analysis confirmed that THEMIS2, a diagnostic biomarker, could distinguish between tumor and normal specimens." (PMID 38589421, 2024). "We analyzed the single-cell RNA sequencing data to investigate the expression pattern of THEMIS2 within the tumor microenvironment." (PMID 39851494, 2025). "High THEMIS2-expressing macrophages exhibited the upregulation of the genes related to cytokine production, tumor promotion, immune suppression, and immune evasion." (PMID 39851494, 2025). "THEMIS2 emerges as a potential biomarker for prognosis and a candidate target for therapeutic intervention aimed at modulating the tumor immune microenvironment." (PMID 39851494, 2025). "In the TCGA-THCA dataset, THEMIS2 was significantly highly expressed in the tumor group compared with the normal group." (PMID 38589421, 2024). "THEMIS2 was significantly upregulated in tumor tissues compared to normal brain tissues." (PMID 39851494, 2025). "Given the crucial role of tumor-associated macrophages (TAMs) in promoting GBM progression and immune suppression, our findings suggest that THEMIS2 may drive TAMs towards a pro-tumorigenic phenotype, supporting tumor growth and immune evasion." (PMID 39851494, 2025). "Additionally, in vivo models are needed to validate the therapeutic potential of THEMIS2 inhibition and assess its impact on tumor progression and TME modulation." (PMID 39851494, 2025). "However, tumor growth was observed in 5 out of the 10 mice implanted with IV2 cells transfected with the THEMIS2-expressing plasmid with tumor latencies of 43, 48, 57, 64, and 71 days respectively." (PMID 34974522, 2022). "As expected, overexpression of THEMIS2 significantly enhanced tumor growth." (PMID 34974522, 2022). "THEMIS2 expression also showed a negative correlation with tumor purity (Rho = −0.584, p = 5.23 × 10−14), suggesting that higher THEMIS2 expression may be associated with a more immune-enriched tumor microenvironment." (PMID 39851494, 2025). "THEMIS2-211 acts as a competing endogenous RNA (ceRNA), sponging miR-940 to upregulate SPOCK1, driving tumor proliferation, invasion, and EMT." (PMID 40303340, 2025). "In one of the two THEMIS2 overexpression groups, CPT (15 mg/kg) was administered by intraperitoneal injection for 7 weeks, starting 1 week after the tumor cells injection." (PMID 34974522, 2022). "Moreover, a high THEMIS2 expression was associated with increased levels of immune checkpoint molecules, such as PD-1, PD-L1, CTLA-4, and HAVCR2, indicating that THEMIS2 might contribute to establishing an immunosuppressive TME that facilitates tumor immune escape." (PMID 39851494, 2025). "Combining THEMIS2-targeted therapies with immune checkpoint inhibitors could potentially transform the immunologically “cold” TME of GBM into a “hot” one, increasing tumor immunogenicity and improving patient outcomes." (PMID 39851494, 2025). "Therapeutically, targeting THEMIS2 could modulate the immune response by altering TAM function, reducing immune suppression, and enhancing T-cell-mediated anti-tumor responses." (PMID 39851494, 2025).
tumor (continued). "Inhibiting THEMIS2 may represent a novel strategy to reprogram TAMs from a pro-tumorigenic to an anti-tumorigenic phenotype, thereby modulating the TME to support effective anti-tumor immunity." (PMID 39851494, 2025).
infection (4 papers, 2010 to 2023). The state of being infected such as from the introduction of a foreign agent such as serum, vaccine, antigenic substance or organism. "Similarly, in an infectious disease model, infection of mice with influenza virus led to a complete but transient loss of Themis2 expression in whole splenocytes that broadly coincided with peak levels of weight loss, an indirect measure of lung inflammation." (PMID 20644716, 2010). "After the peak of NK cell response, the proportion of active Caspase 3/7+ Ly49H+ NK cells was smaller in Themis2-/- mice than in WT mice on days 7, 17, and 28 post-infection." (PMID 37938555, 2023). "Similarly, previous studies had shown that expression of Themis2 in macrophages is reduced in mice undergoing infection or inflammation." (PMID 24907343, 2014). "Thus, Themis2 does not appear to play an important role in the immune response to infection by influenza virus." (PMID 24907343, 2014). "Finally, Themis2 was not required for Ab responses either to T-independent or T-dependent model Ags, or to influenza virus during the immune response to infection." (PMID 24907343, 2014).
THEMIS2 also shares sentences with these, for which no sentence is quoted: infectious disease (2 papers); atherosclerosis (1); ductal carcinoma (1); influenza infection (1); myeloid leukemia (1); viral infections (1).